RPL35A (ribosomal protein L35a)
Diseases named in the same sentence as RPL35A in open-access papers (continued):
Sharing a sentence is not in itself a finding about the gene and the disease.
ovarian carcinoma (continued). "Overall, all these in vitro experiments provided evidence of the critical inhibitory effect of RPL35A knockdown in the malignant progression of ovarian cancer cells." (PMID 38436544, 2024). "In contrast, RPL35A‐overexpressed ovarian cancer cells showed stronger proliferation compared with control cells (p < 0.01)." (PMID 38436544, 2024). "As expected, ovarian cancer cells with overexpression of RPL35A showed enhanced migration (p < 0.001)." (PMID 38436544, 2024). "Furthermore, RPL35A affected the proliferation and apoptosis of ovarian cancer cells through PPAR signalling pathway." (PMID 38436544, 2024). "Accordingly, RPL35A possessed a stimulative effect on human ovarian cancer cells." (PMID 38436544, 2024). "Relationship between RPL35A expression and tumour characteristics in patients with ovarian cancer." (PMID 38436544, 2024). "Moreover, correlation of RPL35A with clinicopathologic characteristics of human ovarian cancer was analysed." (PMID 38436544, 2024). "Therefore, our objective was to investigate the potential significant role of RPL35A in ovarian cancer, with the aim of establishing a theoretical foundation for targeted therapy in the treatment of this disease." (PMID 38436544, 2024). "Our data identified that RPL35A expression was abnormally elevated in ovarian cancer." (PMID 38436544, 2024). "In summary, our findings suggest that the progression of ovarian cancer is driven by RPL35A through the promotion of the YY1‐CTCF binding, and targeting this process could be an effective therapeutic approach for this disease." (PMID 38436544, 2024). "Moreover, the effect of RPL35A on ovarian cancer cell invasion was further confirmed through Transwell experiments, which showed a significant inhibition of invasion ability in shRPL35A HO‐8910 and SK‐OV‐3 cells compared to shCtrl cells (p < 0.05)." (PMID 38436544, 2024). "In ovarian cancer, our data shows that the expression of RPL35A is abnormally high." (PMID 38436544, 2024). "To further evaluate the importance of RPL35A in ovarian cancer, we explored at the cellular level." (PMID 38436544, 2024). "Collectively, RPL35A regulated ovarian cancer progression through CTCF in vitro and in vivo." (PMID 38436544, 2024). "Consistently, our data revealed that CTCF knockdown could partially reverse the regulation of RPL35A overexpression on ovarian cancer cells." (PMID 38436544, 2024). "Furthermore, through cytofunctional validation, we found that RPL35A knockdown resulted in decreased proliferation, migration and enhanced apoptosis of ovarian cancer cells." (PMID 38436544, 2024). "In conclusion, RPL35A drove ovarian cancer progression by promoting the binding of YY1 and CTCF promoter, and inhibiting this process may be an effective strategy for targeted therapy of this disease." (PMID 38436544, 2024). "As expected, RPL35A expression was abnormally elevated in ovarian cancer." (PMID 38436544, 2024). "Consistently, RPL35A regulated ovarian cancer progression depending on CTCF in vitro and in vivo." (PMID 38436544, 2024). "Thus, we suggested that RPL35A regulated ovarian cancer progression depending on CTCF." (PMID 38436544, 2024). "Collectively, RPL35A may promote proliferation and inhibit apoptosis of ovarian cancer cells." (PMID 38436544, 2024). "Furthermore, the relationship between RPL35A expression and clinicopathologic features in ovarian cancer patients, such as age, grade, stage, tumour size, T Infiltrate (T), lymphatic metastasis (N), metastasis (M) and recurrence, was analysed using the Mann–Whitney U test." (PMID 38436544, 2024). "The current study conducted Firefly luciferase & Renilla luciferase and CHIP assays, which revealed that overexpression of RPL35A facilitated the direct interaction between transcription factor YY1 and CTCF in ovarian cancer cells." (PMID 38436544, 2024). "Clinically, high expression of RPL35A predicted short survival and poor TNM staging in patients with ovarian cancer." (PMID 38436544, 2024).
ovarian carcinoma (continued). "Therefore, the mechanism of RPL35A and CTCF regulating ovarian cancer progression required to be further explored." (PMID 38436544, 2024). "Firstly, we interfered with the expression of RPL35A and CTCF in ovarian cancer cells, and named empty vector (negative control), RPL35A (RPL35A overexpression), shCTCF (knocked down CTCF) and RPL35A + shCTCF (simultaneously upregulated RPL35A and downregulated CTCF)." (PMID 38436544, 2024). "In addition, compared to the control group, the relative input rate of CTCF was increased in HO‐8910 and SK‐OV‐3 cells due to the overexpression of RPL35A (p < 0.001), suggesting that RPL35A could promote the direct binding of transcription factor YY1 to CTCF in ovarian cancer cells." (PMID 38436544, 2024).
Alzheimer disease (1 paper, 2025). A progressive, neurodegenerative disease characterized by loss of function and death of nerve cells in several areas of the brain leading to loss of cognitive function such as memory and language. "Alzheimer’s disease (AD) is a neurodegenerative disease, in which reports of the lncRNA SNHG10/OIP5-AS1-miR-3158-3p-RPL35A network contributed to AD pathogenesis via affecting the amyloid precursor protein." (PMID 40251826, 2025).
brain tumours (1 paper, 2024). "Additionally, RPL35A has been associated with the development of malignant brain tumours and may aid in identifying new targets for their diagnosis and treatment." (PMID 38436544, 2024).
colorectal cancer (1 paper, 2025). A primary or metastatic malignant neoplasm that affects the colon or rectum. "Additionally, RPL35A has been suggested to interact with DEAD‐box3, potentially modulating the E2F pathway and immune responses in colorectal cancer." (PMID 40552444, 2025).
diabetes (1 paper, 2016). "We have identified some potential lncRNAs, such as Rpl31-ps7, AB352974, Rpl35a-ps7, Rn4.5s, and XLOC_01985, associated with diabetes-related phenotypes." (PMID 27119337, 2016).
influenza infection (1 paper, 2013). "Evidence exists for an association between influenza infection and the subsequent differential regulation of several genes in our list, such as cadherin 1, ATPase, mago-nashi homolog, proteasome 26S subunit, and ribosomal protein L35a." (PMID 23521892, 2013).
leukemia (1 paper, 2025). A malignant (clonal) hematologic disorder, involving hematopoietic stem cells and characterized by the presence of primitive or atypical myeloid or lymphoid cells in the bone marrow and the blood. "We used K562 leukemia cell line to examine the impacts of reduced levels of specific RP transcripts, RPS10, RPL35A (the ortholog of C. elegans rpl-33), RPL5, and RPS23." (PMID 39786340, 2025).
lung adenocarcinoma (1 paper, 2025). A carcinoma that arises from the lung and is characterized by the presence of malignant glandular epithelial cells. "Analysis of RNA sequencing data from 516 lung adenocarcinoma and 59 normal tissue samples in The Cancer Genome Atlas (TCGA) revealed significantly higher RPL35A expression in tumor tissues compared to normal controls." (PMID 41241099, 2025).
lung squamous cell carcinoma (1 paper, 2025). "Collectively, our findings suggest that RPL35A may serve as a valuable prognostic biomarker for lung squamous cell carcinoma (LUSC) patients and a promising therapeutic target." (PMID 41241099, 2025).
melanoma (1 paper, 2025). A malignant, usually aggressive tumor composed of atypical, neoplastic melanocytes. "The custom-designed 10× Xenium gene panel contained 30 human genes, including pathologically established BCR and S100A1 melanoma markers and RPL23 and RPL35A as the most representative members of the melanoma CTC signature." (PMID 39831781, 2025). "Furthermore, we found four RPL/RPS members of the melanoma CTC signature (RPL23, RPL35A, RPL6, and RPS18) of 21 RPL/RPS genes to be keenly involved in metastatic progression." (PMID 39831781, 2025).
pancreatic cancer (1 paper, 2024). "CTCF‐knocked‐down HO‐8910 and SK‐OV‐3 cells showed a significant inhibition of proliferation and migration (p < 0.001), which was consistent with the role of RPL35A knockdown in pancreatic cancer cells." (PMID 38436544, 2024).
tumor (12 papers, 2017 to 2025). "Recent studies show that RPL35A is significantly upregulated in various human tumours and closely linked to tumorigenesis and malignant progression." (PMID 39871432, 2025). "The regulation of NCAPG2 by RPL35A may represent a critical mechanism underlying RPL35A‐driven tumor progression." (PMID 40552444, 2025). "Notably, the silencing of NCAPG2 effectively reversed the tumor‐promoting effects induced by RPL35A in HCC cells, underscoring the regulatory association between RPL35A and NCAPG2." (PMID 40552444, 2025). "RPL35A is identified as a pro‐carcinogenic factor, demonstrating increased expression in multiple tumour types." (PMID 39871432, 2025). "Histological examinations, including HE staining and IHC staining of the tumor tissues, indicated decreased Ki67 expression upon RPL35A silencing." (PMID 40552444, 2025). "RPL35A has been identified as a biomarker in tumor angiogenesis and exhibits elevated expression levels across multiple tumor types." (PMID 41241099, 2025). "In this study, we demonstrate that RPL35A acts as a tumour promoter in TNBC, suggesting its potential as a promising new therapeutic target." (PMID 39871432, 2025). "The decreased expression of Ki67 in the RPL35A-knockdown group further supports the notion that RPL35A plays a crucial role in promoting tumor proliferation." (PMID 41241099, 2025). "When comparing tumor volume between the groups, we observed that RPL35A depletion significantly decelerated tumor growth." (PMID 40552444, 2025). "It has been reported that RPL35A is mainly involved in the development of Diamond‐Blackfan anaemia and acts as a biomarker in tumour angiogenesis." (PMID 39871432, 2025). "Further weighing of the tumor tissues revealed a significant reduction in tumor weight following RPL35A knockdown." (PMID 40552444, 2025). "IHC results consistently demonstrated elevated RPL35A expression in tumor tissues compared to adjacent non-tumor tissues." (PMID 41241099, 2025). "By observing tumor growth and monitoring tumor volume changes, we found that RPL35A knockdown significantly slowed down the tumor growth rate." (PMID 41241099, 2025). "These were suggested that RPL35A played a tumor-promoting role in tumor progression, but its role in CCA was unclear." (PMID 38395908, 2024). "In vivo, HSPA8 downregulation also inhibited tumor growth and decreased Ki-67 protein expression in tumor tissues, which was opposite to the effect of RPL35A overexpression on tumor growth." (PMID 38395908, 2024). "IHC staining experiments consistently confirmed that, CTCF knockdown partially reversed the regulation of RPL35A overexpression on the proliferation marker KI67 in tumour tissues." (PMID 38436544, 2024). "Compared with the control group, tumour size of RPL35A overexpression group was the largest (p < 0.05), while CTCF knockdown group was the smallest (p < 0.01)." (PMID 38436544, 2024). "In contrast, HSPA8 knockdown suppressed tumor growth, while was able to restore the effects of RPL35A overexpression." (PMID 38395908, 2024). "High expression of RPL35A was observed in 60 out of 107 tumour tissues (56.1%) and in one out of eight adjacent normal tissues (12.5%; p < 0.001)." (PMID 38436544, 2024). "The depletion of RPL35A with both pooled and four individual siRNAs preferentially inhibited growth of tumor cell lines." (PMID 28223711, 2017). "In vivo xenograft models confirm that RPL35A depletion significantly inhibits tumor growth." (PMID 41241099, 2025). "Furthermore, hematoxylin and eosin (H&E) and IHC staining of tumor sections revealed significantly reduced expression of the proliferation marker Ki67 in the RPL35A-knockdown group." (PMID 41241099, 2025). "Moreover, western blotting revealed that, compared to the control group, RPL35A protein was significantly decreased in tumours with upregulation of Smurf2." (PMID 39871432, 2025). "This compelling evidence underscores RPL35A's role as a facilitator of tumor development in HCC." (PMID 40552444, 2025).
tumor (continued). "Furthermore, Spearman correlation analysis confirmed a significant positive correlation between high expression of RPL35A and tumour grade, stage, TNM and recurrence." (PMID 38436544, 2024). "Interestingly, knockdown of CTCF partially reversed the promotion of tumour growth by RPL35A overexpression (p < 0.01)." (PMID 38436544, 2024). "Immunohistochemical staining detected the protein level of Ki67 in tumor tissues, and found overexpression of RPL35A upregulated Ki67 protein, and knockdown of HSPA8 downregulated Ki67 protein, which was consistent with the change trend of cell proliferation in vitro." (PMID 38395908, 2024). "RPL35A can be involved in tumor progression and plays a role as a biomarker in tumor angiogenesis." (PMID 37519793, 2023). "In addition, RPL35A has been reported as a tumour angiogenesis marker." (PMID 39871432, 2025). "To delve deeper into the role of RPL35A in the progression of HCC in vivo, we established a xenograft tumor model by subcutaneously injecting SK‐HEP‐1 cells, with varied RPL35A expressions, into the right flank of nude mice." (PMID 40552444, 2025). "In conclusion, our results demonstrate that RPL35A binds to MYC via its 2 to 22 amino acid residues, thereby facilitating MYC-dependent SKP2 transcription, enhancing glycolysis, and promoting tumor progression." (PMID 41241099, 2025). "Further in vivo experiments suggested that RPL35A overexpression significantly accelerated tumor growth in vivo, whereas HSPA8 knockdown significantly slowed tumor growth." (PMID 38395908, 2024). "Cell experiments and subcutaneous tumorigenesis experiments in nude mice were performed to evaluate the effects of RPL35A and HSPA8 on the proliferation, apoptosis, cell cycle, migration of CCA cells and tumor growth in vivo." (PMID 38395908, 2024). "Taken together, RPL35A was upregulated in CCA and promoted the proliferation and migration of CCA cells and tumor growth." (PMID 38395908, 2024). "This study establishes that RPL35A promotes tumour growth in triple‐negative breast cancer (TNBC)." (PMID 39871432, 2025). "Moreover, RPL35A overexpression increased NCAPG2 levels, promoting tumor progression." (PMID 40552444, 2025). "In addition, studies showed that HSPA8 was a key molecular regulator of chaperone-mediated autophagy, we should further explore whether RPL35A regulates autophagy through HSPA8 and thus plays a tumor-promoting role in the progression of CCA." (PMID 38395908, 2024).
cancer (11 papers, 2017 to 2025). A tumor composed of atypical neoplastic, often pleomorphic cells that invade other tissues. "As an essential component of the 60S ribosomal subunit, RPL35A depletion has been shown to significantly inhibit the growth of various cancer cells." (PMID 41241099, 2025). "Wound healing and Transwell migration assays consistently revealed that RPL35A knockdown markedly impaired the migratory capacity of the cancer cells." (PMID 41241099, 2025). "Beyond its role in ribosomal biogenesis, RPL35A has been implicated in Diamond–Blackfan anemia (DBA), a ribosomopathy associated with heightened cancer susceptibility." (PMID 41241099, 2025). "In our study, we initially corroborated the heightened expression of RPL35A across various cancers, including HCC, using data from the TCGA database." (PMID 40552444, 2025). "Our observations indicate that this phenomenon is also evident in OSCC tissue, particularly characterized by elevated levels of RPL35A in cancer tissues, which correlates with an unfavorable prognosis." (PMID 38256104, 2024). "The RPL35A gene is situated on the chromosomal band 3q29-qter and plays a crucial role in facilitating protein synthesis, therefore serving as a biomarker for cancer angiogenesis." (PMID 38256104, 2024). "Through the immunohistochemical staining analysis of 88 cases of CCA tissues and 5 cases of para-carcinoma tissues, the expression of RPL35A protein in CCA tissues was demonstrated to be higher than that in para-carcinoma tissues." (PMID 38395908, 2024). "This indicates that RPL35A might also have direct anti-apoptotic, extra-ribosomal functions in cancer cells." (PMID 36831382, 2023). "DBA variants in patients with cancer/MDS refer mainly to RPS19, RPL35A, RPL11, RPL5, RPS17, and GATA1 genes (18%, 13%, 10%, 5%, 3%, and 3%, respectively; 49% unknown)." (PMID 38002903, 2023). "Furthermore, in the majority of cancer datasets available in TCGA, the expression level of RPL35A mRNA is higher than in corresponding normal tissues." (PMID 28223711, 2017). "Besides, the expression of RPL35A in CCA and para-carcinoma tissues was determined by immunohistochemical staining, which indicated that the expression of RPL35A was significantly higher in CCA, and was negatively correlated with the overall survival of patients with CCA." (PMID 38395908, 2024). "The siRNA depletion of 3 genes - ARCN1, DDX24, and RPL35A - significantly inhibited the growth of all three cancer cell lines but not normal cells." (PMID 28223711, 2017). "RPL35A may serve as a promising biomarker for various human cancers, but its specific role and mechanisms in triple‐negative breast cancer (TNBC) remain unclear and require further investigation." (PMID 39871432, 2025). "It is therefore not surprising that depletion of only three genes – ribosomal protein RPL35A, COPI subunit ARCN1, and RNA helicase DDX24 – selectively inhibited the growth of all three cancer cell lines without strong effects on BJ-hTERT cells." (PMID 28223711, 2017).
infection (2 papers, 2023 to 2025). The state of being infected such as from the introduction of a foreign agent such as serum, vaccine, antigenic substance or organism. "We observed a significant increase in RPL35A expression following infection with the overexpression lentivirus, and this upregulation was not affected by the transfection of the shNCAPG2 lentivirus." (PMID 40552444, 2025). "Conversely, overexpressing RPL35A markedly elevated NCAPG2 levels in cells, which was reversed upon co‐infection with shNCAPG2." (PMID 40552444, 2025).
infectious disease (1 paper, 2024). A disorder directly resulting from the presence and activity of a microbial, viral, or parasitic agent in humans. "Overrepresentation analyses of upregulated proteins yielded six Reactome pathways enriched, highlighting “HSA-5663205: Infectious disease” (strength = 1.19; FDR = 0.003), which included the proteins RPL18A, PSMA5, HSPA1B, RPL35A, and ISG15." (PMID 39409176, 2024).
RPL35A also shares sentences with these, for which no sentence is quoted: osteosarcoma (2 papers); anemia (1); Bloom syndrome (1); bone marrow failure syndrome (1); Bowen-Conradi syndrome (1); cholangiocarcinoma (1); glaucoma (1); glioma (1); osteoporosis (1); rapadilino syndrome (1); Stroke (1); T-cell leukemia (1); Treacher-Collins syndrome (1); Werner syndrome (1).